TNF (tumor necrosis factor)
Diseases named in the same sentence as TNF in open-access papers (continued):
Sharing a sentence is not in itself a finding about the gene and the disease.
endothelial dysfunction (continued). "This TNF-α-mediated signaling pathway accelerates thrombosis, vascular remodeling, endothelial cell apoptosis, and vascular oxidative stress, all of which are closely associated with endothelial dysfunction." (PMID 41601490, 2026). "The common genetic mutation of MELAS (3243 A > G) causes complex I deficiency causing muscle fatigue and is complicated by endothelial dysfunction with atherogenic and pro-inflammatory properties including upregulation of inflammatory genes, such as IL-6 and TNF-α." (PMID 40142856, 2025). "IL-32’s interplay with TNF-α and other inflammatory mediators is known to drive synovial inflammation and endothelial dysfunction, both of which could further heighten CV risk in this patient population." (PMID 40299461, 2025). "Likewise, TNF-α, a classic M1 macrophage cytokine, is elevated in PE and contributes to endothelial dysfunction; higher TNF-α levels are associated with more pronounced maternal symptoms and fetal growth restriction." (PMID 40722994, 2025). "ENOS expression, influenced by IFN-γ and TNF-α, may affect T. gondii defenses, but excessive nitric oxide can cause endothelial dysfunction." (PMID 40141288, 2025). "On the other hand, neutrophil activation is also linked to increased IL‐6 and TNF‐α levels, which enhance endothelial dysfunction and promote a prothrombotic state, thereby explaining the association between high NLR and increased risk of stroke and systemic embolism." (PMID 39985306, 2025). "IL-6, more than TNF-α, may drive endothelial dysfunction and altered vascular reactivity associated with postoperative hypertension." (PMID 41010423, 2025). "The upregulation of inflammatory cytokines, such as TNF-α and IL-6, causes endothelial dysfunction, manifested by the increased production of adhesion molecules, enhanced vascular permeability, and promotion of endothelial cell proliferation and migration of vascular smooth muscle cells." (PMID 38666951, 2024). "Higher levels of serum TNF-α were associated with an increased expression of circulating isoform of miR-146a-5p and miR-155-5p and overexpression of these miRNAs was associated with endothelial dysfunction and impaired vessel relaxation." (PMID 38909168, 2024). "Proinflammatory mediators including TNF-α and IL-6, in addition to ROS, are known to increase the risk of endothelial dysfunction by inhibiting the bioactivity of NO and eNOS and by upregulating the expression of many atherosclerotic factors via the NF-κB pathway." (PMID 38068901, 2023). "The biological mechanisms underlying this association are thought to include mainly oxidative stress, systemic inflammation (e.g., interleukin-1β, tumor necrosis factor-α, interleukin-6, and C-reactive protein), and endothelial dysfunction caused by prolonged high SUA levels." (PMID 37004085, 2023). "Hypertension has been associated with endothelial dysfunction and a proinflammatory state i.e. higher Angiotensin II levels, chemokines, and cytokines, including interleukin-6 (IL-6) and tumor necrosis factor-α (TNF-α)." (PMID 36251715, 2022). "Although the cause of endothelial dysfunction in KD remains unknown, endothelialactivation and endothelial dysfunction are presumably due to increased cytokineproduction (e.g., IL-1, IL-6, and TNF) by immune effector cells via theNF-κB pathway." (PMID 39076622, 2022). "The high expression of LOX-1 induced by TNF-α is associated with endothelial dysfunction." (PMID 35401507, 2022). "Increased levels of TNF-α and IL-6, through increased production of reactive oxygen species, may lead to endothelial dysfunction with an increased risk of CVDs and less optimal overall outcomes." (PMID 35683564, 2022). "A possible mechanism for these findings is the secretion of inflammatory factors from central or visceral adipose tissue such as tumor necrosis factor-alpha and interleukin-6 which causes endothelial dysfunction at the glomerular level, resulting in an increase in urine albumin excretion." (PMID 34461808, 2021).
endothelial dysfunction (continued). "In mouse models, increased IL-17 was associated with reactive oxygen species formation, circulating inflammatory leukocytes and endothelial dysfunction, while higher levels of resistin, TNF-α, IL-1β, and MMP-9 expression were associated with the levels of inflammatory infiltrates in artery walls." (PMID 33868242, 2021). "Prolonged TNF-α production is associated with endothelial dysfunction." (PMID 32684834, 2020). "Vascular damage related to the main risk factors of CVDs is characterized by endothelial dysfunction, formation and liberation of inflammatory cytokines such as TNF-α, prolonged activation of the systems producing ROS, and eventually, a decrease in endothelial bioavailability of NO." (PMID 32121175, 2020). "Furthermore, in addition to LPS, other pro-inflammatory stimuli, including oxidized low-density lipoprotein (ox-LDL) and TNF-α, also cause endothelial dysfunction, resulting in the initiation of inflammatory responses in numerous cardiovascular diseases." (PMID 31375092, 2019). "Interestingly, these cytokines, in particular TNFα, IL-6, and IL-18, have been associated with endothelial dysfunction, carotid atherosclerosis, CV morbidity, and risk of CV events and mortality in patients with systemic RDs." (PMID 30619884, 2018). "We found no changes in levels of ADMA, making competitive inhibition of eNOS as a cause of the endothelial dysfunction less likely; however, the associated inflammatory response, specifically the inhibitory effect of TNF-α on eNOS, may play a role." (PMID 28673038, 2017). "DHA may contribute to the inhibition of inflammation induced by TNF-α, and consequently may reduce the risk of atherosclerosis as a consequence of endothelial dysfunction." (PMID 28619112, 2017). "We show that TNFα-driven endothelial oxidative stress, in part from eNOS uncoupling, causes endothelial dysfunction and exacerbates endothelial inflammatory response and that these effects can be prevented by treatment with TNFα+tetrahydrobiopterin (BH4) or TNFα+peg-SOD." (PMID 25874717, 2015). "Pharmacologic agents directed against TNF-α-mediated inflammation may decrease the risk of endothelial dysfunction and cardiovascular disease in these patients." (PMID 24968272, 2014). "Indeed, endothelial dysfunction is frequently present in RA patients, even in the absence of identifiable CV risk factors and improves with anti-TNF-α therapy." (PMID 16207339, 2005). "Notably, and in comparison with matched sedentary healthy controls, the collective cohort of patients (long COVID and ME/CFS) exhibited elevated levels of ET-1, VCAM-1, and TNF-α, as well as reduced levels of NOx, signifying underlying inflammation and endothelial dysfunction." (PMID 38600563, 2024). "Besides, releases of proinflammatory cytokines such as interleukin (IL)-6 and tumor necrosis factor (TNF)-α could induce endothelial dysfunction, which was also associated with incident CKD." (PMID 38172903, 2024). "Additionally, TNF has a detrimental effect on endothelial nitric oxide synthase (eNOS) promoter activity, compromising nitric oxide (NO) bioavailability, a hallmark of endothelial dysfunction." (PMID 37834170, 2023). "Furthermore, TNF-α causes endothelial dysfunction, which may contribute to the formation and rupture of atherosclerotic plaques." (PMID 37187788, 2023). "The present study aimed to determine whether TNF-α monotherapy impacts the expression of miRNA-146a-5p and miRNA-155-5p, and whether altered expression of these miRNAs is associated with endothelial dysfunction and impaired vascular reactivity in collagen-induced arthritis (CIA)." (PMID 35213638, 2022). "Moreover, miRNA expression may be induced through several cytokines and the effects of TNF-α inhibition on the expression of miRNAs associated with endothelial dysfunction is uncertain." (PMID 35213638, 2022). "Several TNF-α-mediated mechanisms may cause endothelial dysfunction in RA." (PMID 35887981, 2022).
endothelial dysfunction (continued). "Endothelial dysfunction is prevented by a high antioxidant diet, which is linked to reduced levels of pro-inflammatory cytokines in the plasma Moreover, pro-inflammatory cytokines like IL-6 and TNF- may also suppress BDNF expression." (PMID 34580389, 2021). "Besides, hypertension is associated with endothelial dysfunction and a pro-inflammatory state, which includes higher levels of Ang II, chemokines, and cytokines, including interleukin-6 (IL-6) and tumor necrosis factor-α (TNF-α)." (PMID 34012410, 2021). "Similarly, PM2.5 has also been shown to result in endothelial dysfunction and oxidative stress as assessed by measurements of the associated proteins Tumor Necrosis Factor-alpha (TNF-α), intercellular adhesion molecules (iCAM), and vascular cell adhesion molecules (vCAM)." (PMID 28212639, 2017). "Collectively, the available evidence suggests that TNF-α is mechanistically involved in endothelial dysfunction with the loss of ovarian function, but whether TNF-α and inflammation are involved in the decline in endothelial function during the perimenopausal years warrants further study." (PMID 25984561, 2014). "Elevated TNF-alpha levels may cause endothelial dysfunction both directly and indirectly." (PMID 21253506, 2010). "In the context of ISR, monocytes activate the vascular endothelium by secreting pro-inflammatory cytokines (e.g., TNF-α and IL-6), promoting endothelial dysfunction and smooth muscle cell proliferation, ultimately leading to vascular remodeling and restenosis." (PMID 41602327, 2026). "Specifically, cells were challenged with tumor necrosis factor-α (TNF-α) to induce endothelial dysfunction." (PMID 41629568, 2026). "Endpoints assessed included mean changes in plasma inflammatory markers (IL-1β, IL-6, and TNF-α) and endothelial dysfunction markers (syndecan-1), handgrip strength, fatigue scale, and quality of life (QoL)." (PMID 41753154, 2026). "Periodontitis triggers systemic release of inflammatory mediators such as C-reactive protein, interleukin-6, and tumor necrosis factor-α, all of which are established contributors to endothelial dysfunction and atherosclerosis." (PMID 41598548, 2026). "Inflammatory mediators such as IL-6, TNF-α, and IL-1β play a crucial role in cardiovascular disease, particularly in the pathogenesis of atherosclerosis, endothelial dysfunction, and CVD." (PMID 41601490, 2026). "Elevated levels of inflammatory mediators such as C-reactive protein, interleukin-6, and tumor necrosis factor-α contribute to endothelial dysfunction, promote lipid deposition, and accelerate atherogenesis." (PMID 41598548, 2026). "Elevated levels of inflammatory cytokines such as IL-6, TNF-α, and CRP have been associated with cartilage degradation, endothelial dysfunction, and metabolic dysregulation." (PMID 40843198, 2025). "Elevated LPS enhances monocyte and macrophage activation, inducing pro-inflammatory cytokines (TNF-in IL-6, IL-1,i that aggravate endothelial dysfunction and promote hypertension." (PMID 41503037, 2025). "TNF-α contributes to endothelial dysfunction by damaging the polysaccharide envelope, increasing the expression of adhesion molecules, and promoting apoptosis, ultimately leading to DIC." (PMID 40226813, 2025). "In the context of IR, adipose tissue produces increased levels of pro-inflammatory mediators like TNF-α and IL-6, which can worsen endothelial dysfunction and accelerate vascular calcification." (PMID 40421241, 2025). "Widespread endothelial dysfunction is a central pathological mechanism in dengue-related complications due to the overproduction of inflammatory mediators, such as tumor necrosis factor-alpha (TNF-α), interleukin-6 (IL-6), and interferon-gamma (IFN-γ)." (PMID 40357076, 2025). "It is well known that a complex interplay of factors contributes to the pathophysiology of endothelial dysfunction in T2D, including hyperglycemia, as well as inflammatory cytokines, such as TNF-α." (PMID 40002359, 2025).
endothelial dysfunction (continued). "Pro-inflammatory agents like tumor necrosis factor-α (TNF-α), interleukin-6 (IL-6), interleukin-1β (IL-1β), and vascular endothelial growth factors can further exacerbate vascular injury and endothelial dysfunction, leading to vascular remodeling." (PMID 40933377, 2025). "The ROS-induced oxidation of the IκB kinase complex activates nuclear factor kappa B (NF-κB), driving the transcription of proinflammatory cytokines (e.g., IL-6, TNF-α) and mediators of endothelial dysfunction." (PMID 40332110, 2025). "Once in the bloodstream, LPS triggers systemic inflammation and contributes to endothelial dysfunction by upregulating inflammatory cytokines such as interleukin-6 (IL-6) and tumor necrosis factor-alpha (TNF-α)." (PMID 40361641, 2025). "As far as infliximab is concerned, this TNFα antagonist has been previously reported to improve endothelial dysfunction in different diseases." (PMID 40943589, 2025). "Subsequently, adipose tissue secretes pro-inflammatory cytokines such as TNF-α, IL-6, and resistin, while reducing protective adipokines like adiponectin, contributing to IR, endothelial dysfunction, and systemic inflammation, a process termed metaflammation." (PMID 40959347, 2025). "Endothelial dysfunction induced by tumour necrosis factor (TNF) and platelet activation triggered by interleukin-6 (IL-6) lead to tissue factor expression on platelets and monocytes, enhancing thrombin generation and fibrin formation." (PMID 40943137, 2025). "A study on animals demonstrated that perirenal fat directly led to endothelial dysfunction in the renal artery, partially through the action of tumor necrosis factor-α." (PMID 40340924, 2025). "IL-1β and IL-6 are key drivers of endothelial dysfunction and plaque destabilization, while TNF-α is involved in amplifying the inflammatory cascade and enhancing cellular adhesion, making them particularly relevant therapeutic targets." (PMID 40727466, 2025). "The protective role of GLP-1 in cases of endothelial dysfunction induced by TNF-α is mediated by adjustment of plasminogen activator inhibitor-1 mRNA, adhesion molecules expression, and protein secretion." (PMID 40136627, 2025). "The current body of evidence reveals several consistent patterns, most notably the strong association between chronic periodontal inflammation and systemic endothelial dysfunction, mediated by proinflammatory cytokines such as IL-6, TNF-α, and CRP." (PMID 41294894, 2025). "The inflammatory response triggered by pneumonia involves a cascade of cytokines, including IL-6, TNF-α, and IL-1β, which contribute to endothelial dysfunction and myocardial stress." (PMID 40151738, 2025). "Cytokines such as interleukin (IL)-6, tumor necrosis factor-alpha (TNF-α), and IL-1β have been implicated in the inflammatory cascade, leading to endothelial dysfunction and myocardial stress, thereby increasing the susceptibility to arrhythmias." (PMID 40151738, 2025). "Endothelial dysfunction induced by cytokines (IL-1, IL-6, TNF-α) increases capillary permeability and interstitial oedema, while activation of the renin-angiotensin-aldosterone system and natriuretic peptides exacerbates venous congestion and organ damage." (PMID 40585555, 2025). "Cytokines such as interleukin- (IL-6) and tumor necrosis factor-alpha (TNF-α) promote endothelial dysfunction and plaque instability, precipitating clinical events like myocardial infarction." (PMID 40662044, 2025). "Excessive cytokine synthesis and release, including tumor necrosis factor-alpha (TNF-α), interleukin-1 (IL-1), and IL-6, result in systemic inflammation and endothelial dysfunction." (PMID 41185804, 2025). "Proinflammatory cytokines such as TNF-α, IL-6, IL-8, and IL-18 contribute to endothelial dysfunction by upregulating adhesion molecules in ECs and leukocytes, thereby promoting leukocyte recruitment and vascular inflammation." (PMID 41155389, 2025).
endothelial dysfunction (continued). "First, cytokines such as IL-6, TNF-α, and IL-1β, which are typically elevated in malignancy, promote endothelial dysfunction, upregulate adhesion molecules, and activate platelets." (PMID 41583284, 2025). "This review highlights the main mechanisms linking RA and CVD, including endothelial dysfunction, pro-inflammatory cytokine pathways (IL-1, IL-6, TNF, and JAK-STAT), and the presence of conventional cardiovascular risk factors." (PMID 40283183, 2025). "Influenza infection triggers a surge in cytokines like IL-1β, IL-6, and TNFα, which contribute to endothelial dysfunction, increased monocyte recruitment, and macrophage infiltration into plaques, making them more prone to rupture." (PMID 41439053, 2025). "In RA, early endothelial dysfunction is driven by inflammatory cytokines including tumor necrosis factor-α (TNF-α), interleukin (IL)−1, and is reflected by increased C-reactive protein (CRP)." (PMID 41015607, 2025). "TNF-α is well known for its influence on cardiovascular disease by influencing endothelial dysfunction, atherosclerotic plaque formation, and vascular remodeling." (PMID 40278353, 2025). "The hierarchical analysis demonstrates that TNF-α retains its prognostic value for predicting MACE after accounting for endothelial dysfunction (FMD) and systemic inflammation (IL-6)." (PMID 40310443, 2025). "The engulfment of apoptotic lymphocytes by macrophages can stimulate, rather than suppress, further pro-inflammatory cytokine production (e.g., TNF-α), creating a vicious cycle that perpetuates endothelial dysfunction and plaque growth." (PMID 41163676, 2025). "Studies involving genetically modified mice that lack adiponectin or overexpress TNF-α in adipose tissue have demonstrated accelerated endothelial dysfunction and plaque formation, underscoring the pivotal role of PVAT in modulating endothelial health." (PMID 40943241, 2025). "In particular, oxidative stress and the chronic release of inflammatory cytokines, especially TNF-α and IL-6, promote extensive endothelial dysfunction in axSpA patients." (PMID 40075844, 2025). "These foam cells release cytokines such as tumor necrosis factor-α (TNF-α) and interleukin-1β (IL-1β), exacerbating endothelial dysfunction and sustaining local inflammation." (PMID 41347045, 2025). "Early stages: Inflammation-related genes (e.g., IL6, TNF-α) show significantly elevated expression, reflecting endothelial dysfunction and inflammatory infiltration." (PMID 39858645, 2025). "The expression of TNF-α increases the production of ROS, leading to endothelial dysfunction in many pathophysiological states." (PMID 41471131, 2025). "Dysbiosis involving Actinomyces has been associated with increased levels of pro-inflammatory cytokines such as TNF-α and IL-6, which contribute to endothelial dysfunction." (PMID 40005617, 2025). "IL-32 contributes to vascular inflammation by inducing IL-6 and TNF-α, enhancing endothelial dysfunction and pro-atherogenic lipid changes." (PMID 40937212, 2025). "Visceral adiposity is often accompanied by abnormal secretion of pro-inflammatory factors (e.g., tumor necrosis factor alpha, interleukin 6) by adipocytes and increased free fatty acids, which promote endothelial dysfunction and vascular stiffness." (PMID 40778272, 2025). "Persistent endothelial dysfunction and elevated inflammatory markers (IL-6, TNF-α) have been documented in long COVID patients for at least 6 months post-infection." (PMID 41471341, 2025). "Cytokine-mediated inflammation, particularly through TNF-alpha and IL-6, contributes to endothelial dysfunction, hypoxia, and vascular remodelling, ultimately leading to diminished cardiovascular integrity as disease activity increases." (PMID 39891687, 2025).